PPHLN1 (periphilin 1)
Description:
RNA-binding component of the HUSH complex, a multiprotein complex that mediates epigenetic repression of mobile genetic elements, such as retroviruses and transposable elements. The HUSH complex mainly represses LINE-1 (L1) retrotransposons that are still capable of transposition. The HUSH complex is recruited to genomic loci rich in H3K9me3 and is probably required to maintain transcriptional silencing by promoting recruitment of SETDB1, a histone methyltransferase that mediates further deposition of H3K9me3, as well as MORC2, a chromatin remodeler that compacts chromatin. The HUSH complex is also involved in the silencing of unintegrated retroviral DNA: some part of the retroviral DNA formed immediately after infection remains unintegrated in the host genome and is transcriptionally repressed. Within the HUSH complex, PPHLN1 acts as a mRNA-binding component, which specifically binds nascent transcripts of mobile genetic elements, enabling HUSH-dependent silencing of transcripts. Contributes to the maintenance of the HUSH complex at chromatin. As part of the HUSH2 complex, promotes epigenetic repression of interferon-stimulated genes. May be involved in epithelial differentiation by contributing to epidermal integrity and barrier formation.
Synonyms: CR; HSPC206; HSPC232
Tractability: PROTAC: UniProt records ubiquitination sites on it; ubiquitination databases record sites on it; its protein half-life has been measured.
Gene: Protein-coding gene on chromosome 12 (42,238,418 to 42,459,715, forward strand). Ensembl gene ENSG00000134283.
Subcellular location: Nucleus; Cytoplasm; Chromosome
Subcellular location (Human Protein Atlas): Nucleoplasm; Golgi apparatus
Pathways (Reactome):
Gene expression (Transcription): Regulation of endogenous retroelements by the Human Silencing Hub (HUSH) complex
Gene Ontology:
Molecular function: mRNA binding; protein binding; RNA binding
Biological process: constitutive heterochromatin formation; negative regulation of gene expression, epigenetic; negative regulation of type I interferon production; protein localization to heterochromatin; transposable element silencing by heterochromatin formation; negative regulation of DNA-templated transcription
Cellular component: chromatin; chromosome; cytoplasm; heterochromatin; HUSH complex; HUSH2 complex; nucleoplasm; nucleus
Genetic constraint (gnomAD): Loss-of-function variants: 28 observed, 48.13 expected, observed/expected ratio (o/e) 0.58, 90% interval 0.43 to 0.8. The upper end of that interval is the gene's LOEUF score, 0.8, which puts it in group 3 of 6, group 1 being the genes least tolerant of losing a copy. Missense variants: 427 observed, 437.56 expected, observed/expected ratio (o/e) 0.98, 90% interval 0.9 to 1.06. Synonymous variants: 147 observed, 148.07 expected, observed/expected ratio (o/e) 0.99, 90% interval 0.87 to 1.14.
Homologues: Orthologues: chimpanzee PPHLN1 (95% identical), dog PPHLN1 (93% identical), macaque PPHLN1 (89% identical), dog PPHLN1 (88% identical), rabbit PPHLN1 (88% identical), pig PPHLN1 (85% identical), mouse Pphln1 (83% identical), rat Pphln1 (72% identical), guinea pig PPHLN1 (61% identical), tropical clawed frog pphln1 (51% identical), zebrafish pphln1 (37% identical).
Diseases named in the same sentence as PPHLN1 in open-access papers:
PPHLN1 is named in the same sentence as 7 diseases in open-access papers, as found by Europe PMC text mining. Sharing a sentence is not in itself a finding about the gene and the disease. The quoted sentences say what the papers report.
breast carcinoma (1 paper, 2021). "Fusion partners of FGFR2 reported specifically in breast cancer are AFF3, CASP7 and CCDC6, while partners identified in other cancers include TACC and KIAA family members, PPHLN1, NTRK1, BICC1, AHCYL1, OFD1 and SLC45A3." (PMID 34344433, 2021).
retinoblastoma (1 paper, 2024). A malignant tumor that originates in the nuclear layer of the retina. "Group 3 MB and retinoblastoma, along with the normal cerebellum and retina —both of which are known to express high levels of OTX2—exhibited unique PPHLN1 and MADD splicing patterns." (PMID 39025928, 2024).
tumour (1 paper, 2024). "Among the OTX2-regulated differentially spliced genes, PPHLN1 is expressed in the most primitive rhombic lip stem cells, and targeting PPHLN1 splicing reduces tumour growth and enhances survival in vivo." (PMID 39025928, 2024). "Similar results were obtained following treatment of MB3W1 tumourspheres, as PPHLN1-Mo also significantly inhibits tumour properties, but MADD-Mo induces only a modest but significant increase in tumoursphere size." (PMID 39025928, 2024). "Given the reduction in group 3 MB tumoursphere size and number following one-time PPHLN1-Mo treatment and the sustained exon skipping over 15 d in vitro, we hypothesized that PPHLN1-Mo would be sufficient to impair tumour initiation and growth in vivo." (PMID 39025928, 2024). "Combinatorial therapeutic approaches utilizing PPHLN1-Mo and mTORC1 inhibitors may lead to further decreases in group 3 MB tumour growth." (PMID 39025928, 2024). "Similarly, MB3W1 cells pre-treated with PPHLN1-Mo also exhibited a significantly reduced tumour burden, a significant increase in survival and elevated cell death and differentiation proteins in a representative individual sample from each group." (PMID 39025928, 2024). "The identification of functionally relevant, OTX2-regulated spliced variants of early (PPHLN1) and late (MADD) rhombic lip lineage genes adds complexity to this model, as we now demonstrate a definitive role for alternative splicing program alterations in MB tumour progression." (PMID 39025928, 2024). "Next, we examined the PPHLN1 (exon 6, chr12:42778741–42778798) and MADD (exon 26, chr11:47330530–47330593) splicing patterns across a variety of tumour types (The Cancer Genome Atlas (TCGA)) and normal tissues (Genotype-Tissue Expression (GTEx))." (PMID 39025928, 2024). "Given the rapid tumour progression of our representative MYC-amplified group 3 MB models, the decreased tumour growth and increased survival following one-time treatment with PPHLN1-Mo is encouraging." (PMID 39025928, 2024).
PPHLN1 also shares sentences with these, for which no sentence is quoted: breast invasive carcinoma (1 paper); cancer (1); colorectal cancer (1); viral infection (1).